CYTOR (cytoskeleton regulator RNA)
Diseases named in the same sentence as CYTOR in open-access papers (continued):
Sharing a sentence is not in itself a finding about the gene and the disease.
lymph node metastasis (8 papers, 2017 to 2025). "The established spontaneous lymph node metastasis model also confirmed that CYTOR promoted NPC cell metastasis in vivo." (PMID 31859457, 2020). "According to clinicopathological feature analysis, higher CYTOR expression was observed more frequently in patients with larger tumor size (P = 0.011), advanced TNM stage (P= 0.024) and lymph node metastasis (P = 0.024)." (PMID 30487160, 2018).
renal cell carcinoma (8 papers, 2017 to 2025). "CYTOR has been identified as an oncogene in various cancers, including gastric, hepatocellular, colon, gallbladder, and renal cell cancers 26-29." (PMID 38911384, 2024).
glioblastoma (7 papers, 2017 to 2023). The most malignant astrocytic tumor (WHO grade IV). "The results implied that CYTOR and MIAT may be associated with amplification of PDGFRA and IDH1 mutations, HAR1A may be related with neuron markers in glioblastomas." (PMID 29108264, 2017). "We applied the classification criterion to describe the expression of PVT1, CYTOR, HAR1A and MIAT in glioblastoma subtypes." (PMID 29108264, 2017).
head and neck squamous cell carcinoma (5 papers, 2019 to 2025). A squamous cell carcinoma that arises from any of the following anatomic sites: lip and oral cavity, nasal cavity, paranasal sinuses, pharynx, larynx, and salivary glands. "Importantly, nuclear expression of CYTOR is identified to be the key regulator governing stemness and the p‐EMT phenotype of TB cells, and targeting CYTOR significantly inhibits TB formation, tumor growth and lymph node metastasis in head and neck squamous cell carcinoma (HNSCC)." (PMID 38032139, 2024). "Recent studies have shown that CYTOR interacts with FOSL1 to form phase-separated condensates, which can activate FOSL1-dependent super-enhancers (SEs) to promote tumorigenesis and metastasis in head and neck squamous cell carcinoma (HNSCC)." (PMID 40078192, 2025).
oral cancer (5 papers, 2022 to 2025). "RNA-sequencing of CYTOR-knockdown oral cancer cells revealed that CYTOR can regulate mitochondrial respiration and RNA splicing." (PMID 35963855, 2022). "The results showed that deletion of either CYTOR or HNRNPC promoted the degradation of ZEB1 mRNAs in oral cancer cells." (PMID 35963855, 2022). "Wound healing and transwell assays showed that CYTOR knockdown resulted in decreased migration and invasion behaviors, while CYTOR overexpression resulted in the opposite effect, i.e., elevated migration and invasion, in oral cancer cells." (PMID 35963855, 2022). "Subsequent WB assays confirmed that CYTOR expression levels shared a positive relationship with ZEB1 protein accumulation, and si-CYTOR treatment attenuated ZEB1 protein expression in a dose-dependent manner in both oral cancer cells and 293 T cells." (PMID 35963855, 2022). "Here, we report a survival-related long non-coding RNA, CYTOR, which is highly expressed in the lesions of oral cancer patients." (PMID 35963855, 2022). "We found that CYTOR can promote both migration and invasion in oral cancer cells as well as the epithelial–mesenchymal transition (EMT)." (PMID 35963855, 2022). "By synthesizing CYTOR-targeting small interfering RNAs (siRNAs) encapsulated in Nanoscale Metal Organic Frameworks (NMOFs), we demonstrate the targeted suppression of CYTOR to inhibit invasion and metastasis of oral cancer cells in a nude mouse model." (PMID 35963855, 2022). "In addition, FISH imaging assays and RNA subcellular fractionation together showed that CYTOR localized primarily in the nucleus, and to a lesser extent in the cytoplasm of oral cancer cells." (PMID 35963855, 2022). "lncRNA CYTOR, which promotes EMT and chemoresistance, has been reported to be regulated by FOXD1 transcription in oral carcinoma." (PMID 37563111, 2023). "To our knowledge, we provide the first demonstration of an etiological role for the CYTOR-HNRNPC-ZEB1 axis in regulating both oxidative stress and glycolytic processes in oral cancer invasion." (PMID 35963855, 2022). "In this study, we show that CYTOR regulates ZEB1 via HNRNPC-mediated mRNA stabilization to alter energy metabolism, ultimately facilitating metastasis of oral cancer cells." (PMID 35963855, 2022). "Cumulatively, this study reveals the potential role of the CYTOR-HNRNPC-ZEB1 axis in regulating mitochondrial metabolism and glycolysis of oral cancer cells, and illustrates the effective use of lncRNA targeting in anti-metastatic cancer therapies." (PMID 35963855, 2022). "Collectively, these data indicated that CYTOR could affect the ability of HNRNPC to interact with ZEB1, further enhancing ZEB1 mRNA stability in oral cancer cells." (PMID 35963855, 2022). "5-Ethynyl-20-deoxyuridine (EdU) and CCK-8 assays showed that changes in the expression of CYTOR did not affect the proliferation of oral cancer cells." (PMID 35963855, 2022). "Therefore, we have demonstrated for the first time that CYTOR-HNRNPC-ZEB1 axis promotes the migration and invasion of oral cancer cells through regulating mitochondrial metabolism and glycolysis." (PMID 35963855, 2022). "Collectively, these findings showed that CYTOR could promote EMT, as well as enhanced migration and invasion behavior by oral cancer cells." (PMID 35963855, 2022). "LncRNA CYTOR regulates mitochondrial metabolism and glycolysis of oral cancer cells via HNRNPC-mediated ZEB1 stabilization in oral squamous cell carcinoma, and the level of CYTOR could be upregulated by forkhead box D1 to promote EMT and chemoresistance in oral squamous cell carcinoma." (PMID 36814556, 2023). "To better understand the effects of CYTOR expression in regulating cellular function and metabolism in OSCC, we conducted RNA-seq analysis of the stable CYTOR KD and negative control (NC, scrambled insert) Cal27 oral cancer cells." (PMID 35963855, 2022).
cardiac hypertrophy (4 papers, 2020 to 2026). "The lncRNA CYTOR exerts a protective effect against cardiac hypertrophy by serving as a molecular sponge for miR-155, thereby upregulating IKKi and modulating the NF-κB signaling pathway." (PMID 41602333, 2026). "CYTOR expression in the heart appears to be positively correlated with IKBKE expression, which has been reported to protect the heart from developing pathological cardiac hypertrophy through the IKKi and NF-κB signaling pathway." (PMID 32754048, 2020). "However, unlike CHAR, CYTOR expression is markedly upregulated in response to pressure overload induced cardiac hypertrophy." (PMID 32754048, 2020).
pancreatic cancer (4 papers, 2015 to 2022). "Even more pronounced expression changes were observed for LINC00152, also referred to as CYTOR, whose herein described upregulation in pancreatic cancer confirmed a recent finding using a small cohort of six PDAC and five control tissues." (PMID 32727085, 2020).
Sepsis (4 papers, 2020 to 2022). Sepsis is defined as life-threatening organ dysfunction caused by a dysregulated host response to infection. "As a result of this pathway, the downregulation of CYTOR or the upregulation of miR-24 appeared to exacerbate sepsis-induced myocardial injury via the activation of apoptosis." (PMID 36012630, 2022). "Up-regulation of CYTOR ameliorated viability and inhibited apoptosis in sepsis-induced myocardial injury." (PMID 34956235, 2021). "As a result of this pathway, down-regulation of CYTOR or up-regulation of miR-24 appeared to worsen sepsis-induced myocardial injury via activation of apoptosis." (PMID 33396834, 2020). "Downregulation of CYTOR aggravated sepsis-induced cardiac injury via regulation of miR-24/XIAP." (PMID 34041287, 2021).
nasopharyngeal carcinoma (3 papers, 2020 to 2022). A carcinoma arising from the nasopharyngeal epithelium. "Cytoskeleton regulator RNA (CYTOR) is upregulated in nasopharyngeal carcinoma (NPC) tissues and cells and facilitates the invasion and metastasis of NPC cells." (PMID 31859457, 2020).
tongue squamous cell carcinoma (3 papers, 2020 to 2022). A squamous cell carcinoma that arises from the tongue. "CYTOR, also known as LINC00152, was proved experimentally to be associated with progression and prognosis of tongue squamous cell carcinoma and HNSCC." (PMID 32024523, 2020). "Compared its expression in normal oral epithelial cell line HOK, CYTOR was significantly upregulated in OSCC cell lines, especially in two tongue squamous cell carcinoma cell lines (HN6 and Cal27)." (PMID 35963855, 2022).
triple-negative breast carcinoma (3 papers, 2019 to 2024). An invasive breast carcinoma which is negative for expression of estrogen receptor (ER), progesterone receptor (PR), and human epidermal growth factor receptor 2 (HER2). "In triple-negative breast cancer, the transcription factor YIN-YANG 1 (YY1) was found to inhibit the transcription of CYTOR, thereby acting as an anticancer agent." (PMID 39058104, 2024).
colorectal tumor (2 papers, 2019 to 2020). "Besides the ones that were reported to be dysregulated in colorectal tumor samples, such as CCAT1, H19, DANCR, ZFAS1, SNHG16, CYTOR, we have identified many others in this study including LUCRC." (PMID 32082365, 2019).
adenoma (1 paper, 2020). A neoplasm arising from the epithelium. "LINC00152 (also known as CYTOR) is one of the most extensively investigated lncRNAs in GC, but its expression, promoter DNA methylation and effects during colorectal normal-adenoma-carcinoma sequence progression have not been completely studied yet." (PMID 32307642, 2020).
astrocytoma (1 paper, 2017). "GBM displayed remarkably higher PVT1 and CYTOR expression as compared with oligodendroglioma (P =0.002 and P <0.001), oligoastrocytoma (P =0.015 and P =0.002), and astrocytoma (P =0.011 and P <0.001)." (PMID 29108264, 2017). "GBM demonstrated a significant higher CYTOR and PVT1 expression levels than astrocytoma (A, P <0.001), and oligodendroglioma (OD, P <0.001)." (PMID 29108264, 2017).
COVID-19 (1 paper, 2021). A disease caused by infection with severe acute respiratory syndrome coronavirus 2. "For example, we identify CYTOR, a lncRNA associated with granulocyte survival strongly upregulated in COVID-19 patient group G1, which was accompanied by strong induction of CYTOR interactors such as VIM and PIK3CB." (PMID 33441124, 2021). "Interestingly, expression of CYTOR was significantly increased in severe COVID-19 patient group G1 (p < 0.001) and correlated with both PIK3CB (r = 0.53, p < 0.001) and VIM (r = 0.55, p < 0.001)." (PMID 33441124, 2021).
Duchenne muscular dystrophy (1 paper, 2025). Duchenne muscular dystrophy (DMD) is a neuromuscular disease characterized by rapidly progressive muscle weakness and wasting due to degeneration of skeletal, smooth and cardiac muscle. "We chose to test CYTORexon2,ΨU RNA in myoblasts isolated from Duchenne muscular dystrophy (DMD) patients because these patients have impaired type II muscle fibers, and we found ≈46% reduced CYTOR levels in myoblasts from DMD patients compared to myoblasts from healthy controls." (PMID 39960339, 2025).
kidney cancer (1 paper, 2023). Primary or metastatic malignant neoplasm involving the kidney. "A functional experiment was carried out to learn more about the regulation of kidney cancer by the interaction of lncRNA CYTOR and miR-136-5p." (PMID 36902032, 2023). "In particular, the results showed that lncRNA CYTOR knockdown inhibited renal cancer progression and could be reversed by miR-136-5p." (PMID 36902032, 2023). "Indeed by influencing the miR-136-5-p/MAT2B/BAG3 axis, CYTOR may contribute to kidney cancer." (PMID 36902032, 2023).
liver fibrosis (1 paper, 2024). "Exosomes from damaged cells exacerbated liver fibrosis, while downregulation of CYTOR alleviated liver fibrosis." (PMID 38520214, 2024). "This study was performed on CCl4‐induced damaged liver cells and mouse liver fibrosis models with specific focus on regulation of the GDNF pathway by lncRNA CYTOR." (PMID 38520214, 2024). "Upon downregulation of CYTOR in damaged liver cells, expression levels of liver fibrosis‐related biomarkers were decreased." (PMID 38520214, 2024). "Consistent with in vitro cytological results, our in vivo data showed that levels of miR‐125b and GDNF as well as markers of liver fibrosis underwent changes dependent on the expression of lncRNA CYTOR." (PMID 38520214, 2024). "Notably, downregulation of CYTOR within extracellular vesicles effectively inhibited liver fibrosis." (PMID 38520214, 2024). "Based on the collective findings, we propose that downregulation of lncRNA CYTOR could effectively inhibit the formation of liver fibrosis in vivo, in which exosomes play an important role." (PMID 38520214, 2024). "Additionally, silencing of lncRNA CYTOR reduced the degree of liver fibrosis." (PMID 38520214, 2024). "Finally, we validated the mechanism of action of lncRNA CYTOR in liver fibrosis in vivo." (PMID 38520214, 2024).
muscular dystrophy (1 paper, 2025). Muscular dystrophy (MD) refers to a group of more than 30 genetic diseases characterized by progressive weakness and degeneration of the skeletal muscles that control movement. "Delivery of the chemically enhanced CYTOR exon 2 RNA domain improves disease hallmarks in myotubes derived from muscular dystrophy patients." (PMID 39960339, 2025).
myocardial infarction (1 paper, 2022). Gross necrosis of the myocardium, as a result of interruption of the blood supply to the area, as in coronary thrombosis. "Studies have shown several lncRNA-related ceRNA networks in HCM, such as cardiac hypertrophy-related factor (CHRF), ROR, H19, Plscr4, myocardial infarction-associated transcript, maternally expressed gene three (MEG3), and cytoskeleton regulator RNA (CYTOR)." (PMID 36138345, 2022).
papillary thyroid cancer (1 paper, 2020). "In conclusion, our study reported that TRIM29 inhibited miR-873-5P biogenesis via lncRNA CYTOR sponging premiR-873 to upregulate FN1 and promoted invasion of papillary thyroid cancer cells." (PMID 32994394, 2020).
thyroid cancer (1 paper, 2020). "Online database (starbase.sysu.edu.cn) also exhibited that CYTOR was negativity co-expressed with miR-873-5p and miR-873-3p in thyroid cancer tissues." (PMID 32994394, 2020). "RNA sequence demonstrated that several long non-coding RNAs (LncRNAs) were downregulated by TRIM29 knockdown, and LncRNA CYTOR was screened as online database exhibited that CYTOR was positively co-expressed with TRIM29 and FN1 in thyroid cancer tissues." (PMID 32994394, 2020).
tumor (85 papers, 2015 to 2025). "In addition, the infiltration of numerous immune cells associated with the tumor immune microenvironment, such as neutrophils, monocytes, and fibroblasts, among others, is strongly correlated with CYTOR expression." (PMID 38911384, 2024). "The expression level of CYTOR was examined between normal tissues and tumor samples using TCGA data." (PMID 38394500, 2024). "Consistent with the findings in the subcutaneous xenograft model, a significant decrease in tumor volume was observed in mice treated with both CYTOR ASO‐1 and CYTOR ASO‐2 as compared to control mice." (PMID 38032139, 2024). "The result revealed that the methylation level of CYTOR was significantly higher in normal tissues than in tumor tissues (P<0.05)." (PMID 38911384, 2024). "We analyzed the expression of CYTOR in tumor and normal tissues using the TCGA_SKCM dataset (461 tumor samples and 558 normal samples)." (PMID 38911384, 2024). "After RNA extraction from the tissue samples, qRT-PCR analysis was performed showing that CYTOR expression was significantly higher in tumor tissues (P<0.01)." (PMID 38911384, 2024). "Collectively, these findings support the notion that CYTOR promotes metastasis and tumor growth of HNSCC, which is correlated with decreased overall survival and disease‐free survival in HNSCC patients." (PMID 38032139, 2024). "The overexpression of lncRNA CYTOR in IPA tissues and cell lines was associated with tumor invasiveness and adenoma size of the patients." (PMID 37904679, 2023). "Downregulation of CYTOR inhibited PA cell proliferation, migration, and invasion by sponging miR‐206, suggesting the CYTOR‐miR‐206 axis as a tumor‐promoting factor providing new insights into PA treatment." (PMID 37904679, 2023). "miR-24-3p was significantly downregulated in NPC tumor samples relative to paracancerous controls, while CYTOR was upregulated." (PMID 36814556, 2023). "These cumulative findings provide strong evidence that the CYTOR-HNRNPC-ZEB1 axis regulates energy metabolism in the development of tumor metastasis." (PMID 35963855, 2022). "Co-transfection of CYTOR with miR-125a-5p inhibitor reversed the effect of sh-miR-125a-5p on apoptosis, proliferation, tumor volume and weight, suggesting that CYTOR promotes HCC growth by modulating miR-125a-5p." (PMID 35081873, 2022). "The results indicated that the expression levels CRNDE and CYTOR were significantly correlated (p < 0.05) with tumour grade, age (<40 and ≥40 years), PRS type, 1p19q chromosome codeletion, IDH mutation status and chemotherapy status." (PMID 35359593, 2022). "CYTOR has been reported as an adverse factor of pan cancers via promoting proliferation, migration, invasion, metastasis, and drug resistance of tumor cells." (PMID 33505990, 2020). "Consistent with our observation, the results from these datasets showed significantly up-regulated CYTOR expression in tumor tissue samples." (PMID 30064438, 2018). "The TargetScan prediction algorithm identified tumor-suppressing miR-195 as target microRNAs of CYTOR." (PMID 30487160, 2018). "As tumor budding cells are considered a histological phenomenon of EMT, which contributes to tumor metastasis, we also evaluated the relationship between CYTOR and EMT markers." (PMID 30064438, 2018). "Previous studies have demonstrated that overexpression of cytoskeleton regulator RNA (CYTOR) predicates poor prognosis and promotes tumor progression." (PMID 30487160, 2018). "By contrast, overexpression of CYTOR increased the volume and weight of the xenograft tumors and promoted tumor growth in vivo." (PMID 30064438, 2018). "The findings further expand on the roles played by CYTOR in malignancies and may improve the use of CYTOR in tumor diagnosis and treatment." (PMID 38911384, 2024). "CYTOR expression level in tumor specimens was greater compared to surrounding normal tissues." (PMID 38394500, 2024).